STAT3 (signal transducer and activator of transcription 3)
Diseases named in the same sentence as STAT3 in open-access papers (continued):
Sharing a sentence is not in itself a finding about the gene and the disease.
cancer (continued). "In addition, GBM cancer stem cells have been found to respond to perturbations caused by hypoxia, the inhibition of STAT3 phosphorylation, and IL-6 stimulation." (PMID 34576141, 2021). "Overexpression of STAT3 is associated with poor clinical prognoses of cancer patients." (PMID 33477856, 2021). "STAT3 is an important signaling molecule, and it is closely associated with apoptosis in cancer." (PMID 33585660, 2021). "However, the molecular mechanisms underlying the regulation of STAT3 stability and degradation in the context of cancer cells are unclear." (PMID 34067416, 2021). "Moreover, acetylated STAT3 was revealed to cause gene silencing through enhancing the methylation of estrogen receptor-α gene promoter in cancer cells." (PMID 33859766, 2021). "In contrast, somatic STAT3 mutations are less frequent in cancer." (PMID 33435349, 2021). "For example, IL-6 overproduction by stromal cells supports tumor growth through STAT3 activation, promotes cancer-associated fibroblast (CAF)-induced cancer invasion, and was recently shown to promote resistance of cancer cells to therapy, proving its broad pro-tumorigenic role." (PMID 33923020, 2021). "A previous study has suggested that PIMREG regulates Th17 differentiation and colitis and inflammation-associated cancer by modulating transcriptional activity of STAT3, indicating that PIMREG may be correlated with immune response in the tumorigenesis." (PMID 34594356, 2021). "Tyrosine‐phosphorylated STAT3 is considered the major transcriptionally active form and can contribute to oncogenesis, although nonphosphorylated STAT3 has also been implicated in transcriptional regulation and cancer." (PMID 33605027, 2021). "However, aberrant STAT3 signaling has been linked to many of the hallmarks of cancer, including cell growth, proliferation, survival, immune evasion, metastasis, and angiogenesis." (PMID 34067421, 2021). "STAT3 signaling is also associated with apoptosis control in cancer cells." (PMID 33920736, 2021). "However, in the already established HCC, persistent activation of STAT3 accelerates gene transcriptions associated with cell survival, proliferation, invasion, angiogenesis, and cancer stemness." (PMID 33947048, 2021). "As a key regulator for multiple cellular processes including proliferation, differentiation, immune function and angiogenesis, STAT3 activation has been implicated as a critical mechanism in drug resistance for a range of oncogene driven cancers in targeted therapeutics." (PMID 33391507, 2021). "Recruitment of TECs by cancer cells is associated with activation of JAK/STAT3 signalling via IL-8." (PMID 34834295, 2021). "In a variety of cancers, IL-6 is overexpressed and is associated with the activity of STAT3." (PMID 34445405, 2021). "Here, our data suggested that inactivation of STAT3 pathway signaling was not via the canonical Na+/K+-ATPase on the plasma membrane, and further investigation should be performed to fully illuminate the mechanism underlying the STAT3 inactivation by ouabain treatment in cancer cells." (PMID 34277430, 2021). "STAT3 is closely associated with pathogenesis of various cancers by regulating the expression of critical genes for survival, proliferation, and angiogenesis, such as Bcl-2, Bcl-xL, Mcl-1, CCND1, and VEGF, which were important for survival, proliferation, and angiogenesis." (PMID 34335938, 2021). "Mutations in PTPRD restrict its ability to regulate STAT3, which promotes cancer progression." (PMID 34503185, 2021).
cancer (continued). "However, the sample size of human cancer samples containing STAT3 mutations is low and hence this conclusion needs to be supported by further evidence." (PMID 33535185, 2021). "Angiogenesis is another hallmark of cancer that has been directly linked to STAT3." (PMID 33498872, 2021). "Notably, despite critical roles in processes such as growth, development, apoptosis, infection and cancer, the precise mechanism(s) underlying cytokine-dependent STAT3 nuclear accumulation also remain poorly understood." (PMID 34166464, 2021). "Previous reports showed that extracellular E-cadherin stabilizes the LIFR/gp130 and ErbB2 (HER2)/HER3 complexes to activate STAT3 and Erk1/2 with regard to maintaining the pluripotency of ES cells and is associated with the progression of human cancer, respectively." (PMID 33572536, 2021). "In addition, IGF1R activation determines phosphorylation and nuclear translocation of STAT3, which modulates transcriptional activation of cancer-associated genes." (PMID 33673232, 2021). "Therefore, inhibiting STAT3 activation has potential in cancer therapy, and STAT3 activation is associated with the induction of apoptotic resistance, possibly by increasing Bcl-2 expression." (PMID 34641334, 2021). "Moreover, STAT3 activation through IL-6/IL-11 in cancer associated fibroblasts (CAFs) promoted CRC development and poor prognosis." (PMID 34046355, 2021). "Indeed, chronic inflammation has been demonstrated to lead to JAK/STAT pathway mutations in other cancers, and upregulation of interleukin-6-mediated STAT3 activation has been reported in BIA-ALCL cell lines." (PMID 34638403, 2021). "Thus, S1P/S1PR1 signaling was shown to be closely linked to a persistent activation of STAT3 in cancer cells." (PMID 34289244, 2021). "In addition, the JAK/STAT3 signaling pathway, an intracellular signal transduction closely associated with cancer progression, was inhibited by NR1D1." (PMID 34330232, 2021). "Thus, a small set of STAT3-target genes predicts susceptibility of EBV-unrelated cancer cell lines including blood cancer lines to PARP inhibition." (PMID 33002095, 2020). "Moreover, the Resistin receptors CAP1 and TLR4 mediate the effects of Resistin on cancer cells through activation of STAT3 (signal transducer and activator of transcription 3) and are implicated in the resistance to chemotherapy." (PMID 33072768, 2020). "Aberrant activation of STAT3 is associated with malignant cancers with poor clinical prognosis, and STAT3 inhibition causes cancer cell death, suggesting STAT3 as a potential target for cancer therapy." (PMID 31900385, 2020). "Increasing number of studies show that STAT3 may serve as one of the oncogenic critical factors and is associated with a poor prognosis in certain types of cancer." (PMID 32194797, 2020). "Interestingly, STAT3 has been implicated in cancer cell survival by regulating the transcription of other anti-apoptotic members of the Bcl-2 family, such as BCL2, Bcl-xL, and MCL1." (PMID 33396645, 2020). "Furthermore, sMIC also promotes MDSCs amplification by activating STAT3 and causes macrophages to be more inclined to a more immunosuppressive phenotype, suggesting that sMIC targeting is a target for cancer immunotherapy." (PMID 33224886, 2020). "Hyperactivation of STATs, particularly STAT3, has been implicated in many cancers." (PMID 33521321, 2020). "Several groups have reported elevated STAT3 activity in HPV-associated cancers." (PMID 32899142, 2020). "STAT3 is implicated in the development of chemotherapy resistance in various cancers." (PMID 32046095, 2020). "In addition, FTY720 inhibited the SphK1/S1P/S1PR1 axis and abrogated NF-κB/IL-6/STAT3 signaling, which reduced the severity of colitis and colitis-associated cancer." (PMID 32456134, 2020).
cancer (continued). "Additionally, STAT3 is frequently activated in human cancers and is implicated in the regulation of cancer cell survival, proliferation, angiogenesis and metastasis." (PMID 32807795, 2020). "Interestingly, ratios of drugs associated with STAT3 expression were quite diverse among these cancer cell lines and highly primary-site-dependent." (PMID 32486001, 2020). "The subsequent increase in ROS levels results in DNA damage and is hypothesized to affect multiple oncogenic cellular pathways, including inhibition of the STAT3 signaling pathway, which has been implicated in cancer stem cell viability." (PMID 32236642, 2020). "Moreover, the study have also indicated the association between STAT3 expression and drug response in different cancer cell lines." (PMID 32486001, 2020). "Over 70% of cancers are associated with hyperactivated STAT3." (PMID 32491253, 2020). "STAT3 is a functional signalling protein, and constitutive activation of STAT3 has been implicated in the progression of inflammation and inflammation-associated cancers." (PMID 33082817, 2020). "In addition, the activated STAT3 pathway has been associated with the progression and chemoresistance in ovarian and other cancers." (PMID 33023532, 2020). "The two STAT proteins most extensively associated with cancer development are STAT3 and STAT5." (PMID 32899142, 2020). "Moreover, we analyzed the nuclear translocation of the active STAT3 transcription factor, shown to be involved in the activation processes of cancer-associated fibroblasts." (PMID 32756477, 2020). "In some cancer cells, an mdr1 mRNA downregulation has been associated with a STAT3 inhibition." (PMID 33081075, 2020). "Furthermore, we systematically investigated the association between STAT3 expression and drug response in various cancer cell lines." (PMID 32486001, 2020). "In the literature, the JAK2/STAT3 pathway was frequently associated with cancer metastasis." (PMID 31621555, 2020). "STAT3 regulates the inflammatory processes associated with the induction of metaplasia outbreaks, increases epithelial cell proliferation and appears to be responsible for the development and progression of some cancers." (PMID 32488850, 2020). "STAT3, a transcription factor, regulates the expression of genes involved in the cell cycle, cell survival and immune response associated with multiple carcinoma progression and malignant tumours." (PMID 32869923, 2020). "Furthermore, AR loss enhances the EMT and invasion of cancer through induction of CCL2/CCR2/STAT3 axis." (PMID 31952344, 2020). "Therefore, the signaling pathways involved in the STAT3-associated autophagy are quite intricate particularly in terms of cancer cell chemoresistance." (PMID 31597912, 2019). "STAT3 is also an important regulator of immune cell function, it has been linked to cancer." (PMID 31602271, 2019). "In addition, cancer-associated fibroblasts (CAFs) use STAT3 activity to secrete cytokines that recruit additional immune cells and promote STAT3 activity in other cell types in the TME26–28." (PMID 31796877, 2019). "This phosphorylation site in STAT3 is often mutated in cancers." (PMID 31694222, 2019). "As for rs2293152 located in the 11 intron of STAT3 gene, we are unaware of any study examining its functional relevance, but it is hypothesized that it may influence the cancer risk by affecting gene transcriptional regulation or the process of mRNA splicing." (PMID 31342143, 2019). "In addition, this study also showed that the inhibition of STAT3 phosphorylation by curcumin is able to cause loss of colony formation, and the inhibit migration and invasion of cancer cells." (PMID 31817718, 2019).
cancer (continued). "These include STAT3 and HoxA5, which have been associated with cancer induction." (PMID 31040909, 2019). "This substitution to the STAT3 cancer-associated genotype in STAT5B suggests that the protein may be more optimized for protein dimerization." (PMID 31717342, 2019). "pS727-STAT3, together with STAT3 glutathionylation at residues Cys328 and Cys542, seem to be related to an enhanced oxidative stress and associated with a more advanced cancer form." (PMID 31500219, 2019). "Stat3 and Stat5a/b transcription factors have been implicated in several pathophysiological conditions, and pharmacological inhibition of both transcription factors has been proposed to treat certain diseases, such as malignancies." (PMID 31443474, 2019). "Notably, both of these frequently cancer-associated mutation sites in STAT3 (Tyr640 and Asp661) are by default Phe and Ile respectively in STAT5B." (PMID 31717342, 2019). "STAT3 is activated in many cancers and associates with patient’s survival." (PMID 31324203, 2019). "In addition, we found that TGF-β–Smad pathway engages in crosstalk with the STAT3 pathway in cancer cells harboring a KRAS mutation." (PMID 29969465, 2018). "Therefore, STAT3 activation in macrophages has been associated with a pro-tumoral macrophage phenotype, cancer progression, and poor patient outcome." (PMID 29867925, 2018). "However, the expression of PTPRD containing cancer-specific mutations reversed the inhibitory effect on cell growth and STAT3 phosphorylation." (PMID 30208623, 2018). "However, our study showed that high expression of STAT3 was associated with poor prognosis, indicating that STAT3 was a cancer-promoting factor in UTUC." (PMID 30091994, 2018). "STAT3 mutations have been associated with immunodeficiency, autoimmunity, and cancer." (PMID 30072615, 2018). "Transcriptional factors of the NF-κB family and STAT3 are commonly regulating the expression of various genes associated with cell-cycle progression, angiogenesis, immune responses, apoptosis, metabolism, and cancer." (PMID 29932172, 2018). "Abolishing STAT3 activity may be an attractive cancer therapeutic strategy, while the underlying mechanisms of STAT3 activation deregulation in cancers is largely unknown." (PMID 29950561, 2018). "Indeed, TFF3 acts as a promiscuous activator of multiple survival pathways in cancer cells, including HER1-4, PI3K/AKT, RAS/MEK/MAPK, and cSRC/STAT3, which are critically associated with enhanced cancer cell survival, metastasis, and resistance to therapy." (PMID 30451834, 2018). "Moreover, at the molecular level, STAT3 signaling is complex and cooperates with several other pathways implicated in cancer growth." (PMID 30301213, 2018). "The NF-κB and JAK/STAT3 pathways are very important in driving cancer-associated inflammation." (PMID 29707119, 2018). "Further in vivo studies may provide important leads for using icariin as treatment of cancers carrying STAT3 activating mutations." (PMID 29899697, 2018). "STAT3 signaling is linked to cancer cell plasticity and is able to promote EMT and CSC expansion." (PMID 30065235, 2018). "STAT3 is indeed implicated in mitochondrial calcium control and the reduction in STAT3 in cancer cells observed here following CBD treatment may thus have modulatory effects on EMV release." (PMID 30150937, 2018). "Thus, the STAT3 pathway is thought to be associated with cancer metastasis, and the suppression of this pathway can be used as one of the strategies in cancer therapy." (PMID 29794990, 2018). "Increasing HIC1 expression and/or HIC1–STAT3 interaction could represent a new and promising approach to treat STAT3-associated human cancers." (PMID 29914167, 2018). "STAT3 has been implicated in the maintenance and function of MDSCs in cancer patients." (PMID 29632539, 2018).
cancer (continued). "Studies have shown that Res may cause IL-6 changes in cells and further downregulate the expression of p-STAT3 and NF-κB; the development of Cis resistance is also associated with the continuously activated p-STAT3 and NF-κB in cancer cells." (PMID 29390972, 2018). "STAT3 is phosphorylated by receptor-associated kinase and then forms homo-or heterodimers that translocate to the cell nucleus, where they transcribe a variety of genes that are associated with cancer cell growth and metastasis." (PMID 29242509, 2017). "STAT3 activation is associated with various cancers and suggests poor prognosis." (PMID 28811522, 2017). "Noteworthily, STAT3 has been found closely associated with various human cancers." (PMID 29179470, 2017). "Previous studies demonstrated that STAT3 is intimately associatedwith cancer development." (PMID 28659496, 2017). "The high activation level of STAT3 under hypoxia, an oncoprotein strongly implicated in chemoresistance in cancer cells, has led us to hypothesize that STAT3 sustained the chemoresistant phenotype despite the effective experimental abrogation of HIF-1α." (PMID 29036915, 2017). "The relative indifference of STAT3 phosphorylation to changes in redox environment thus might serve as one of the driving forces of cancer progression associated with poor prognosis." (PMID 28819544, 2017). "Finally, we assessed the effects of compounds KI12 and KI16 on a STAT3-driven cancer-associated phenotype." (PMID 28636670, 2017). "Interestingly, STAT3 upregulation is a hallmark of many cancer models, not only in cancer cells but also in the inflammatory infiltrate." (PMID 29445756, 2017). "STAT3 is also linked to inflammation-related oncogenesis initiated by genetic alterations and environmental factors, and is constitutively activated in various cancers." (PMID 26959884, 2016). "Thus, targeted deletion of SPL in normal intestinal epithelial cells, which increases S1P levels, enhanced colitis-associated cancer through STAT3-modulated regulation of proinflammatory cytokines." (PMID 27800303, 2016). "We further showed reduction of the laminin 5 protein level in spheroid culture of cells that were overexpressed with S727A point-mutated STAT3, but increment of laminin 5 protein level in bulk cancer cells that were overexpressed with S727E point-mutated STAT3." (PMID 27306323, 2016). "However, approximately 70% of human cancers display persistent STAT3 activation, causing induction of oncogenes." (PMID 26700818, 2016). "Our previous study and some other reports have shown that BRG1 loss function mutation is a common mechanism in several kinds of cancers, and this may be one of the reasons behind STAT3 hyperactivity in cancers." (PMID 27145366, 2016). "IL-22 contributes to pro-survival signaling, angiogenesis and metastasis, part of which may be associated with its activation of STAT3 signaling pathway in cancer cells." (PMID 27784305, 2016). "In response to cytokines or growth factors, activated STAT3 functions as a nuclear transcription factor by regulating genes involved in proliferation, survival, angiogenesis and invasion, as well as genes encoding key cancer-promoting inflammatory mediators." (PMID 26887043, 2016). "Considering that deregulation of transcriptional control is a central characteristic of cancers, and inflammation is a defined cancer-causing factor, it is reasonable to presume that alteration of STAT3 may be involved in the process of carcinogenesis." (PMID 27577070, 2016). "Aberrant activation of STAT3 signaling participates in the initiation, development and progression of human cancers via induction of STAT3 downstream genes that encode antiapoptotic proteins, cell cycle regulators and angiogenic factors such as Bcl-2, Cyclin D1 and VEGF." (PMID 27317769, 2016).